ALB (albumin)
Diseases named in the same sentence as ALB in open-access papers (continued):
Sharing a sentence is not in itself a finding about the gene and the disease.
cancer (continued). "For example, nanoparticles coated with bovine serum albumin can induce ferroptosis by releasing metal ions that catalyze the Fenton reaction, producing reactive hydroxyl radicals and enhancing therapeutic efficacy in cancer treatment." (PMID 40927424, 2025). "Several researches have been conducted with a main goal of enhancing ALB aqueous solubility by formulating it as solid-lipid nanoparticles, chitosan-PLGA nanoparticles, albumin nanoparticles, polyurethane nanoparticles which have shown promising results on various cancer cell lines." (PMID 40978467, 2025). "An in-depth understanding of albumin's diverse biological functions may offer new perspectives for optimizing therapeutic strategies and clinical decision-making in cancer care." (PMID 40693202, 2025). "The interaction between indirect bilirubin and albumin may help shield thyroid cells from oxidative damage and contribute to cancer prevention." (PMID 40723913, 2025). "In recent years, many nutrition-related indexes, including prognostic nutritional index (PNI), geriatric nutritional risk index (GNRI), albumin-to-globulin ratio, and C-reactive protein-to-albumin ratio (CAR), represent key markers for predicting cancer prognosis." (PMID 40171257, 2025). "Similarly, while albumin is widely used as an indicator of nutritional status, it is also affected by systemic inflammation, making it less reliable in the context of cancer." (PMID 41195263, 2025). "Therefore, the poor water solubility and oral bioavailability (less than 5%) are considered as obstacles against the clinical use of ALB as anti-cancer drug." (PMID 40978467, 2025). "SRL is commercially available for oral administration as an immunosuppressant given in a daily dosage of 2–10 mg (bioavailability 15 %, e.g., oral Rapamune, Pfizer) and as albumin-bound intravenous formulation (Fyarro) in a dose of 100 mg/m2 for cancer therapy." (PMID 40687897, 2025). "Additionally, the CRP/albumin ratio demonstrated prognostic value in predicting outcomes, especially among patients with malignancies." (PMID 41010574, 2025). "In addition to albumin and lipoprotein nanoparticles, a variety of other types of nanoparticles have shown unique promise for application in cancer therapy through macropinocytosis." (PMID 40723808, 2025). "Notably, globulin (GLO) emerged among the top SHAP-ranked predictors, a finding consistent with prior evidence linking elevated globulin and reduced albumin–globulin ratio to systemic inflammation and poor cancer prognosis." (PMID 41300279, 2025). "Therefore, the encapsulation of PCA into folate-conjugated albumin nanoparticles enhances its efficacy and targeting for cancer cells." (PMID 40670469, 2025). "The success of albumin-based systems is evident in real-world applications like Abraxane, an albumin-bound paclitaxel formulation that has shown improved efficacy and reduced toxicity in cancer therapy compared to its conventional counterpart." (PMID 40699702, 2025). "Serum albumin and hemoglobin levels, as measurable continuous variables, are some of the most commonly used indicators of a patient’s nutritional status and are also used to assess cancer progression and prognosis patients." (PMID 40282930, 2025). "Numerous immune and inflammatory markers—including the neutrophil-to-lymphocyte ratio (NLR), platelet-to-lymphocyte ratio (PLR), lymphocyte-to-CRP ratio, lymphocyte-to-monocyte ratio, and CRP-to-albumin ratio—have been shown to provide prognostic value in cancer patients." (PMID 40836295, 2025). "Low serum albumin levels in cancer patients may reflect their nutritional status and serve as an indicator of their response to adjuvant therapy, as well as the severity of the underlying disease." (PMID 39807216, 2024). "Therefore, some studies used the combination of CRP and albumin to predict the prognosis of cancer patients." (PMID 38803531, 2024).
cancer (continued). "This study uncovers a nonlinear relationship between serum albumin levels and cancer mortality risk, suggesting that the risk of mortality triggered by a decrease in albumin levels is ampl at lower levels of albumin, thus exhibiting threshold effects." (PMID 38500655, 2024). "Albumin is one of the most commonly used indicators for assessing a patient’s nutritional status and has a wide range of potential applications in predicting the prognosis of cancer patients." (PMID 39897534, 2024). "Albumin (n = 29, 55.8%; 3512 participants) was the most used biomarker in cancer cachexia trials." (PMID 38783477, 2024). "Concentrations of biomarkers that were significantly decreased (p < 0.05) in the cohort of cancer patients included albumin, Hb, and lymphocyte count, while white blood cell counts (WBCs), neutrophil counts, and concentrations of CXCL5 and H3Cit were comparable between patients and controls." (PMID 38744744, 2024). "Furthermore, the role of recombinant albumin and albumin-based nanocarriers in drug delivery and cancer therapy is the focus of extensive research." (PMID 39612427, 2024). "Although initial exposure to harmful agents such as carcinogens might boost albumin production, in advanced cancer stages, we often see a marked reduction in albumin levels." (PMID 39195131, 2024). "Decreased albumin levels directly affect the outcome and prognosis of cancer treatment." (PMID 38500655, 2024). "Our findings suggest that higher ALB levels are associated with lower ALP levels in patients with cancer, providing a basis for the prediction and treatment of bone metastases in patients with cancer." (PMID 38552093, 2024). "Thus, albumin is an ideal protein that can serve as an excellent ligand endow nanocarriers with unique properties; the drug release from albumin nanocarriers can be easily regulated because cancer cells efficiently metabolise albumin." (PMID 39456987, 2024). "Plasma albumin levels have also been reported as a clinical predictor of cancer." (PMID 38337485, 2024). "Several methods existed to assess the nutritional status of cancer patients, along with numerous indicators for evaluating nutritional status, such as hematocrit, hemoglobin, albumin, transferrin, heme, serum creatinine, urine creatinine, and BMI, among others." (PMID 39464703, 2024). "Although the related risk of mortality was confirmed after adjustment for sex, age, type of cancer, smoking habits, BMI, albumin, and creatinine levels, the statistical significance was lost by including coagulation parameters and FVIIa-AT in the regression models." (PMID 38282902, 2024). "Additionally, albumin nanoparticles, exemplified by paclitaxel-loaded Abraxane®, have been approved for cancer therapy, highlighting their potential in targeted drug delivery." (PMID 39272576, 2024). "We observed negative associations between these metabolites and overall cancer risk, with the exception of albumin, which showed a positive association." (PMID 39003294, 2024). "In addition, as an indicator of the nutritional status of cancer survivors, albumin level also had important prognostic significance in predicting the survival rate of cancer survivors." (PMID 39592977, 2024). "Albumin is a powerful index of the systemic nutritional status in cancer patients." (PMID 39597034, 2024). "In a univariable logistic regression model including prealbumin and albumin deficiency, as well as low UAMA percentile, pretreatment albumin deficiency was shown to be a significant predictor of 3 or more infectious episodes during cancer treatment (p = 0.02)." (PMID 39619813, 2024). "Furthermore, albumin is one of the efficient biomimetic molecules with a cancer-targeting ability because it can bind the gp60 receptor and SPARC protein, which are overexpressed in several cancer cells." (PMID 39456987, 2024).
cancer (continued). "The results of subgroup analyses suggested a linear negative connection of serum albumin with all-cause mortality in all subgroups, except for white populations age<40, with a BMI of 25–30, and with a cancer history." (PMID 39026682, 2024). "Serum albumin levels, which serve as a measure of preoperative nutritional status, have traditionally been considered one of the most significant prognostic indicators among patients undergoing cancer surgery." (PMID 38877445, 2024). "Thus, pretreatment serum albumin levels offer valuable prognostic significance in cancer, showing the less the albumin value, the worse the prognosis." (PMID 39400724, 2024). "In clinical practice, regular monitoring of albumin levels and electrolytes not only results from the assessment of the patient’s nutritional status, but also from the need to assess the presence of potential treatment and cancer complications." (PMID 38732574, 2024). "However, as the disease advances, there is a substantial decrease in albumin levels, which can effectively act as prognostic indicators for cancer." (PMID 38169970, 2024). "Albumin and prealbumin levels were significantly lower in cancer patients than in controls." (PMID 39619813, 2024). "Restricted cubic spline (RCS) analysis was conducted to assess the nonlinear relationship between serum albumin levels and the risk of cancer mortality." (PMID 38500655, 2024). "Therefore, the FA score, as an integrated index based on the plasma fibrinogen and albumin, reflects the preoperative inflammatory responses of hosts to tumors and the alterations in the cancer microenvironment." (PMID 39440062, 2024). "Physiological dysregulation of cytokines, such as tumor necrosis factor-alpha and interleukin 6, in patients with tumors may impede albumin synthesis by hepatocytes, influencing cancer progression and neoangiogenesis." (PMID 39624689, 2024). "An increase in CRP level with a decrease in Albumin level has been found in many cancers." (PMID 38903332, 2024). "Similarly, the Washington consensus statement identified CAR components CRP (>5 mg/L) and albumin (<3.2 g/dL) as biochemical indicators of cancer-cachexia." (PMID 38975012, 2024). "Low serum albumin levels may lead to decreased immune function, thereby accelerating the growth and spread of cancer cells." (PMID 38745951, 2024). "Furthermore, we showed that harnessing albumin-GAG interactionsincreases cancer cell death induced by paclitaxel-loaded albumin-coatedNPs." (PMID 39470630, 2024). "For example, many studies suggest that the NPAR may predict poor outcomes in patients with various types of cancer, and its predictive capacity is better than that of neutrophil percentage or albumin alone." (PMID 38178381, 2024). "Various inflammatory markers, including neutrophil-to-lymphocyte ratio (NLR), monocyte-to-lymphocyte ratio (MLR), platelet-to-lymphocyte ratio (PLR), and C-reactive protein-to-albumin ratio (CAR), have been linked to the effectiveness of immunotherapy in multiple types of malignancies." (PMID 39132507, 2024). "However, limited data exists on the survival benefits of improving albumin, reducing lymphocytes, or improving monocytes in cancer patients." (PMID 38337485, 2024). "Moreover, efforts should be made to fully develop and utilize various scoring models related to albumin to better serve cancer patients." (PMID 38500655, 2024). "These factors lead to a swift decline in serum albumin levels among cancer patients." (PMID 39080372, 2024). "This tool is based on the CRP and albumin levels at the time of diagnosis of advanced cancer." (PMID 39330032, 2024). "In addition, albumin can be used as a carrier to transport cancer-targeting drugs and food components." (PMID 38500655, 2024). "In the cancer group, albumin and prealbumin levels were higher after vs. before treatment." (PMID 39619813, 2024).
cancer (continued). "Additionally, Serum ALB is another well-known and frequently used biomarker that reflects liver function and nutritional status of patients with various cancers." (PMID 38834790, 2024). "Hemoglobin and albumin levels reflect nutritional status, while lymphocytes and platelets provide insights into the body's immune status, all of which have known implications in the initiation and progression of cancer." (PMID 38716011, 2024). "Additionally, the possibility of chemically modifying albumin allows the integration of specific functional groups, which can enhance targeting specificity to cancer cells and regulate the drug release rate from the carrier." (PMID 39796113, 2024). "Albumin may improve the long-term survival of cancer patients by reducing disease complications and unexpected deaths through anti-inflammatory and anti-thrombotic effects." (PMID 38500655, 2024). "The nanoparticle albumin-bound strategy has allowed the creation of some effective anti-cancer nanoparticle drugs that are available on the market, like Abraxane nab-paclitaxel developed by Abraxis BioScience and Fyarro nab-sirolimus developed by Aadi Bioscience." (PMID 38257777, 2024). "Low serum albumin is encountered quite frequently in children treated for cancer." (PMID 39305296, 2024). "Serum albumin is a frequently utilized indicator for evaluating nutritional status, and numerous studies have demonstrated that low serum albumin levels are an autonomous predictor of poor survival for diverse cancers." (PMID 38310276, 2024). "Albumin-based therapeutic nanoprobes, with multimodal imaging and photothermal therapy capabilities, as well as a “photothermal ablation-assisted surgery” strategy, hold promise for clinical cancer therapy in the future." (PMID 39771471, 2024). "Furthermore, the nonlinear relationship suggests the importance of choosing the appropriate timing for albumin infusion in cancer patients." (PMID 38500655, 2024). "Notably, PPI use remained a significant factor in our Cox multivariate analysis as well as cancer metastasis and serum albumin level." (PMID 39664993, 2024). "In cancer, the serum titer of such autoantibodies is significantly lower in advanced disease compared to healthy controls presumably due to a high production of the antigens, the albumin neo-structures, including IL-6IF." (PMID 39518029, 2024). "We hypothesized that BBC-IP would enhance water solubilitycompared to biotin, interact with albumin, and exert biotin-mediateduptake on cancer cells that previously have shown that they do notinternalize PBC-IP." (PMID 39758612, 2024). "The prognostic value of low albumin levels has been confirmed in cancer patients with cachexia." (PMID 38438901, 2024). "In addition, the strong noncovalent affinity of QA-photoCORM to albumin enables use of an albumin: QA-photoCORM complex for targeted CO delivery to cancer cells." (PMID 38742651, 2024). "A decrease in serum albumin levels can lead to a reduction in the sequestration of unbound reactive molecules, thereby enhancing the probability of deleterious cellular damage that can induce cancer development." (PMID 38476986, 2024). "Interestingly, more of these albumin neo-structures were generated in PBMC cultures from advanced cancer patients compared to healthy controls." (PMID 39518029, 2024). "The ability of albumin to target tumors as a carrier for vaccines is because albumin can provide a large number of the nutrients needed for rapid cancer cell proliferation, allowing the presence of receptors on cancer cell surfaces that are capable of binding to albumin." (PMID 38611742, 2024). "However, the current study found the opposite result for predicting survival in patients with cancer cachexia: albumin had the most accurate prognostic value, followed by transferrin and prealbumin." (PMID 38438901, 2024). "ALB is involved in multiple pathways related to metabolism and cancer development." (PMID 39502516, 2024).
cancer (continued). "So, the authors suspected that there could be multiple contributors to the final feature of low albumin level, but this point should be paid more attention to in cancer-related septic children." (PMID 38797509, 2024). "RCS analyses revealed a stable nonlinear negative association between albumin levels and cancer mortality in all groups, regardless of confounder adjustment." (PMID 38500655, 2024). "However, due to small sample size we did not analyze patients grouped according to infections severity, but we assessed the impact of prealbumin and albumin deficiency and PEU on the incidence of infectious complications during cancer treatment." (PMID 39619813, 2024). "RCS analyses highlighted a consistent and negative nonlinear relationship between albumin levels and cancer mortality risk within all patient groups, with or without the adjustment for confounding factors." (PMID 38500655, 2024). "Moreover, supplying cancer cells with albumin during treatment with an inhibitor of the mammalian target of rapamycin (mTOR) boosts albumin breakdown in lysosomes." (PMID 39353906, 2024). "An independent predictor of malignant tumours was serum albumin." (PMID 39816318, 2024). "Therefore, our study aimed to thoroughly investigate and compare the value of albumin, prealbumin and transferrin in predicting survival and QoL in patients with cancer cachexia." (PMID 38438901, 2024). "Application of phenolic compounds encapsulated by albumin NPs in cancer research." (PMID 39070787, 2024). "Additionally, the related influencing factors for patients with normal serum iron are found to be CRP, albumin, total cholesterol, and cancer staging." (PMID 38562035, 2024). "Chronically ill patients, such as cancer patients, often have low albumin levels." (PMID 39596952, 2024). "Therefore, when screening high-risk populations of cancer survivors, we should specifically focus on individuals with simultaneous increases in CRP levels and decreases in albumin levels." (PMID 39358685, 2024). "In the presence of tissue hypoxia, albumin releases NO to maintain vascular tone, which may be beneficial for cancer prognosis." (PMID 38500655, 2024). "Reduced albumin is synonymous with increased inflammation and may therefore be useful in predicting the extent of cachexia in cancer patients." (PMID 38744744, 2024). "Due to elevated hemoglobin and albumin concentrations, angiogenesis may increase protein signaling in malignant tumors, indicating NAC-induced angionecrosis may potentially be examined by APTw." (PMID 38298813, 2024). "A 70-year-old male was admitted to the Hubei Cancer Hospital with complaints of left-sided limb weakness and numbness persisting for one month after completing the first cycle of albumin paclitaxel, cisplatin, and tislelizumab treatment for right-sided NSCLC in December 2021." (PMID 39296984, 2024). "We chose this IC50 dose to analyze albumin–chlorogenic acid NPs anti-cancer effects in vitro." (PMID 37176983, 2023). "Although chronic malnutrition diseases, such as cancer and liver or kidney diseases, reduce serum albumin levels, the low serum albumin level seen in patients with acute critical illnesses, such as STEMI, is caused by the increased catabolism and decreased synthesis of albumin." (PMID 37745131, 2023). "Furthermore, there were significantly greater differences in both liver and renal function in cancer subjects as cancer subjects had lower albumin levels, higher urea and protein levels (p < 0.05)." (PMID 35642123, 2023). "PNI is calculated as a prognostic factor for cancer using lymphocyte count and serum albumin." (PMID 37043179, 2023). "In vitro studies reveal that cancer cells utilize albumin as an alternative source of nutrients." (PMID 36597205, 2023). "Albumin-to-globulin ratio (AGR) is the combination of nutritional and inflammatory indicator, and its high expression level is closely associated with longer survival time in cancer patients." (PMID 37828259, 2023).